RN7SL38P (RNA, 7SL, cytoplasmic 38, pseudogene)
Gene: Miscellaneous RNA gene on chromosome 12 (24,706,788 to 24,707,083, forward strand). Ensembl gene ENSG00000240481.
Homologues: Orthologues: chimpanzee Metazoa_SRP (99% identical), macaque Metazoa_SRP (92% identical). Paralogues in human: RN7SL1 (84% identical), RN7SL2 (84% identical), RN7SL3 (83% identical), RN7SL45P (83% identical), RN7SL126P (81% identical), RN7SL769P (81% identical), RN7SL336P (80% identical), RN7SL220P (80% identical), RN7SL7P (80% identical), RN7SL88P (80% identical), RN7SL122P (79% identical), RN7SL650P (79% identical), and 704 more.